MTX1LP (metaxin 1 like, pseudogene)
Synonyms: MTX1P; MTX1P1; MTXP; psMTX
Gene: Transcribed unprocessed pseudogene on chromosome 1 (155,230,975 to 155,234,325, forward strand). Ensembl gene ENSG00000236675.
Diseases named in the same sentence as MTX1LP in open-access papers:
MTX1LP is named in the same sentence as 1 disease in open-access papers, as found by Europe PMC text mining. Sharing a sentence is not in itself a finding about the gene and the disease.
MTX1LP shares sentences with these, for which no sentence is quoted: tumour (1 paper).